KLF17 (KLF transcription factor 17)
Diseases named in the same sentence as KLF17 in open-access papers (continued):
Sharing a sentence is not in itself a finding about the gene and the disease.
tumor (22 papers, 2010 to 2026). "In this study, we firstly identified that high tumor KLF17 expression is associated with favorable prognosis in patients with OSCC." (PMID 32019121, 2020). "Overall, a higher KLF17 expression level was associated with several clinicopathological factors, such as female gender and early tumor stage." (PMID 32019121, 2020). "The scores by the pathologists for the intensity of the KLF17 expression in the nuclei revealed that KLF17 expression was significantly associated with tumor stage and T-value." (PMID 32019121, 2020). "Recent studies have shown that low expression and inactivation of KLF17 can be due to microRNA expression, gene mutations, or the loss of heterozygosity in human tumors, all of which are involved in tumor progression." (PMID 32019121, 2020). "Decreased KLF17 expression is already an independent prognostic indicator for most human tumors, and low expression is significantly associated with tumor progression." (PMID 32019121, 2020). "Further studies elucidated that the low expression of KLF17 was associated with carcinoma progression, and suppression of KLF17 expression promotes tumor cell migration, invasion, and EMT shift." (PMID 26662959, 2016). "Recent studies have demonstrated that KLF17 low expression and inactivation are caused by microRNA, gene mutation, and loss of heterozygosity in human tumors, which participates in tumor progression." (PMID 26662959, 2016). "The reduced expression of KLF17 is an independent prognostic indicator of the majority of human tumors, and it is significantly associated with tumor progression." (PMID 26662959, 2016). "The KLF family member, KLF17, also promotes epithelial differentiation and associates with the tumor suppressor actions of TGFβ signaling." (PMID 27367735, 2016). "Our results indicate that loss of KLF17 impairs tumor suppressive function of TGF-β/Smad-dependent pathway." (PMID 25766320, 2015). "However, underlying mechanisms leading to tumor suppressive and anti-metastatic function of KLF17 still remains unknown." (PMID 25766320, 2015). "High KLF17 expression in tumor tissue can serve as a prognostic marker for a favorable survival in patients with OSCC." (PMID 32019121, 2020). "Kaplan–Meier analysis confirmed the relationship between patient survival based on different tumor stages and KLF17 expression, as patients with advanced stage disease or low KLF17 expression had poor outcomes." (PMID 32019121, 2020). "KLF17 exerts its tumor suppressor function by interacting with the promoters of EMT-related genes; it was at first identified as a novel tumor suppressor from a forward genetic screen in a mouse model." (PMID 26662959, 2016). "Here, we show that KLF17 plays an integral role in potentiating TGF-β/Smad signaling via Smad3-dependent pathway to suppress tumor progression." (PMID 25766320, 2015). "In this study, we provide new insights into the anti-metastasis and tumor suppressive function of KLF17." (PMID 25766320, 2015). "For example, KLF family proteins have been shown to have either a tumor-promoting (KLF4, KLF6, KLF9, KLF10, KLF11, and KLF17) or a tumor-suppressing (KLF5, KLF12) role by intervening in cell signaling associated with proliferation and/or suppression." (PMID 26320172, 2015). "By contrast, high KLF17 expression can inhibit tumor growth." (PMID 32019121, 2020). "However, tumor metastasis is a result of many genes’ concerted action, the precise mechanism of KLF17-involved metastasis is still incomplete, and much more challenges for researchers need to be overcome." (PMID 26662959, 2016). "Since KLF17 was at first identified as a tumor suppressor, an increasing number of studies have reported that KLF17 is frequently downregulated, which is correlated with tumor progression in various human cancers." (PMID 26662959, 2016). "Thus, TGFβ, via Smad3, induces KLF17 expression, and KLF17 suppresses tumor growth, providing input to the cytostatic action of TGFβ." (PMID 27367735, 2016).
tumor (continued). "KLF17 is downregulated and correlated with tumor progression in various human cancers." (PMID 26662959, 2016). "We found that KLF17 potentiates TGF-β/Smad-dependent signaling to inhibit tumor formation." (PMID 25766320, 2015). "In addition to cytostatic effect, KLF17 is also critical for tumor-suppressor function of TGF-β in regulating cell cycle and cell death." (PMID 25766320, 2015). "Moreover, inhibition of KLF17 expression could induce tumor cell proliferation and metastasis and was related to poor prognosis in PTC." (PMID 37817224, 2023). "We also evaluated the association between DNA methylation and mRNA expression of KLFs in PCa tumour tissues and found that the mRNA expression of most KLFs was negatively associated with its DNA methylation at the promoter region (P < .05), except for KLF3, KLF9 and KLF17." (PMID 32281273, 2020). "In the EMMAX corrected dataset rs6698333, an intron variant of Kruppel-like factor 17 (KLF17) and two SNPs (rs1889877, rs3798999) in the intron of adhesion G protein-coupled receptor B3 (ADGRB3) were significantly (< 10-5) associated with ERG fusion status of the index tumor." (PMID 32341752, 2020). "Of 22 differentially methylated promoters common between all LS tumor groups, seven inversely correlated with expression: ADHFE1, DAPP1, FBLIM1, GRIA4, HOXA3, KLF17, and ZNF528." (PMID 40753397, 2025). "Our earlier study revealed that artificial circular single‐stranded DNA (CSSD) can restore the expressions of multiple tumour suppressor genes, KLF17, E‐cadherin and LASS2 and inhibit the malignant progression of tumours." (PMID 36855796, 2023). "A recent study shows that KLF17 is a key regulator of TGF-β signaling pathway, and it has the capacity to suppress tumor progression through potentiating TGF-β/Smad3-dependent signaling pathway." (PMID 26662959, 2016). "In addition, as a negative regulator of EMT and metastasis in LUAD, KLF17 regulated the Smad3-dependent pathway to enhance TGFβ1/SMAD signaling, and was a key link in anti-tumor metastasis or growth." (PMID 38560274, 2024). "KLF17 is a negative regulator of EMT and functions as a tumor suppressor." (PMID 33510281, 2021). "Knockdown of Klf17 led to EMT and promoted tumor metastasis." (PMID 23284647, 2012). "Importantly, we observed an inverse correlation between KLF17 expression and HCC tumor grades, suggesting that decreased expression of KL17 may be associated with poor prognosis." (PMID 25766320, 2015).
cancer (16 papers, 2014 to 2024). A tumor composed of atypical neoplastic, often pleomorphic cells that invade other tissues. "Our results showed an upregulation of KLF17, a TF whose upregulation is negatively associated with cell motility in different human cancer cell lines." (PMID 38162669, 2023). "Taken together, these findings indicate that repressed KLF17 is associated with cancer cell phenotype transition and contributes to cancer progression." (PMID 26662959, 2016). "Low expression of KLF17 is associated with cancer progression." (PMID 33510281, 2021). "The deregulation of either KLF17 or SMAD3 would diminish the ability of TGF-β to inhibit cancer cells." (PMID 36761967, 2023). "KLF17 inhibits cancer cell invasion in lung adenocarcinoma by suppressing the phosphorylation of p38 MAPK and inhibiting the urokinase fibrinogen activator induced by p38 MAPK/SRC signaling pathway." (PMID 36761967, 2023). "Many studies that have focused on the function of KLF17 in tumorigenesis have reported that KLF17 plays a vital role in cancer development." (PMID 32019121, 2020). "Recently, many reports have focused on KLF17 functions in tumorigenesis and found that KLF17 plays an important role in cancer development." (PMID 26662959, 2016). "Taken together, these studies indicate that suppressed KLF17 in human cancers promotes metastasis through inducing ID1." (PMID 26662959, 2016). "Here, in this study we address the issue that how KLF17 control cancer progression and metastasis in cancer cells." (PMID 25766320, 2015). "Among the highly correlated cancer samples, two displayed low levels of KLF17 and Smad3 expression (KLF17− and Smad3−)." (PMID 25766320, 2015). "Compared with control cells, KLF17-depleted cell lines were less sensitive to anti-cancer drug treatment." (PMID 25766320, 2015). "In contrast to Smad-inactive (HCT116) and Smad4 null (MDA-MB-468) cancer cell lines, we observed higher levels of KLF17 in Smad-expressing cells such as HepG2, MCF-7, HaCaT and H1299." (PMID 25766320, 2015). "Even though growing evidence suggests that KLF17 is involved in the inhibition of metastasis and EMT, great efforts are still needed to further understand KLF17 regulation during cancer progression." (PMID 25766320, 2015). "We indentified that KLF17 has a key role to potentiate TGF-β/Smad-dependent pathway to suppress cancer progression." (PMID 25766320, 2015). "To investigate the physiological function of KLF17 on cytostatic behavior in cancer cells, we measured cell growth capacity with manipulated expression of KLF17." (PMID 25766320, 2015). "Knockdown of KLF17 expression in multiple cancer cell lines showed similar decrease in Smad3 mRNA levels, substantiating that KLF17 induces Smad3 expression in multiple cells." (PMID 25766320, 2015). "Whilethe modulation mechanism remains unclear, there is evidence that melatonincould modulate the DJ-1/KLF17/ID-1 signaling pathway to prevent theexcessive mitotic activities, as shown with the occurrence of cancer." (PMID 37676068, 2023). "In addition, KLF17 suppresses the invasion of cancer cells through its interactions with CD44, PAI-1, Cyclin-D1." (PMID 28454121, 2017). "In the present study, we summarized KLF17’s function in cancer process and its mechanism." (PMID 26662959, 2016). "KLF17 low expression increases cancer metastatic viability; its mechanism is that low KLF17 mediates epithelial-mesenchymal transition (EMT) through regulating EMT-related genes expression; the reduced-KLF17 also increases cancer metastasis though upregulating inhibitor of DNA binding 1 (ID1)." (PMID 26662959, 2016).
cancer (continued). "While, depletion of Smad3 reduced KLF17 expression in different cancer cells." (PMID 25766320, 2015). "FACS analysis showed that HepG2 cells were less susceptible to cisplatin-induced apoptosis when KLF17 was depleted, suggesting that KLF17 may increase cellular sensitivity to anti-cancer chemotherapy." (PMID 25766320, 2015). "Furthermore, we show that KLF17 increases the sensitivity of cancer cells response to anti-cancer drugs." (PMID 25766320, 2015). "KLF17 shows positive correlation with Smad3 levels in cancer samples." (PMID 25766320, 2015). "Functionally, depletion of KLF17 enhanced tumorigenic features in cancer cells." (PMID 25766320, 2015). "Interestingly, KLF17 expression was strongly correlated with Smad3 level in all tested cancer samples except 1 (labeled as KLF17+ and Smad3+)." (PMID 25766320, 2015). "To determine the physiopathological relevance of KLF17 with human cancer development, we analyzed clinical data to see whether KLF17 expression correlated with disease progression in human HCC." (PMID 25766320, 2015). "Next, we examined KLF17 RNA expression in several human cancer cell lines." (PMID 25766320, 2015). "This could serve as a clue as to why KLF17 inhibits EMT in one cancer type but promotes EMT instead in another cancer type." (PMID 25485290, 2014). "Moreover, in this report, we investigated a previously unknown regulatory mechanism for the regulation of KLF17 by TGF-β/Smad3 signaling in cancer cells." (PMID 25766320, 2015). "Thus, induction of KLF17 by TGF-β/Smad3 may be one of the mechanisms to fight against cancer development." (PMID 25766320, 2015). "Finally, our study indicates that targeting KLF17 for cancer therapy may be beneficial for some human tumors having abnormal Smad3 proteins." (PMID 25766320, 2015). "Regulation of cell growth by KLF17 may have significant impact on cancer chemotherapy." (PMID 25766320, 2015). "Our mechanistic study provides an insight to the well-known observation that both KLF17 and TGF-β/Smad3 can regulate ID1 and impinge on cancer cell metastasis." (PMID 25766320, 2015). "By inspecting the human exitron list, we found that EIS affects several cancer-related genes: the cancer marker genes BMI1, KRT5, and MUC1 and the genes involved in cell adhesion (CSF1), migration and metastasis (ZEB2 and KLF17)." (PMID 25934563, 2015). "However, the molecular details that how KLF17 control cancer metastasis remains unclear." (PMID 25766320, 2015). "KLF17 is a crucial regulator of TGF-β signaling, which forms a positive feedback loop with SMAD3, and the expression of both is often positively correlated in cancer tissues." (PMID 36761967, 2023). "In silico predictions indicated that a metastatic suppressor gene such as KLF17 and two cellular protein, RBM10 and TOX3 which are involved in proliferation and apoptosis of cancer cells could be the actors influencing the outcome of BRAF inhibitor therapy." (PMID 25437182, 2014).
infection (1 paper, 2023). The state of being infected such as from the introduction of a foreign agent such as serum, vaccine, antigenic substance or organism. "Altogether, our results show that the SHK-1 macrophage-like cell line infected by P. salmonis shows a regulatory cascade with KLF17 as an essential regulator at early times of infection." (PMID 38162669, 2023). "Together, our results suggest that the upregulation of KLF17 in SHK-1 cells infected by P. salmonis could be suppressing the cell motility of the infected macrophages at early infection times and probably promoting an M2-like phenotype in infected macrophages." (PMID 38162669, 2023).
KLF17 also shares sentences with these, for which no sentence is quoted: hepatocellular carcinoma (4 papers); colorectal carcinoma (2); esophageal cancer (2); myoepithelial neoplasms (2); adenocarcinoma (1); adenoma (1); bile duct cancer (1); colon cancer (1); intestinal cancer (1); oral cancer (1); Oral Squamous Cell Carcinoma (1); ovarian carcinoma (1); papillary thyroid carcinoma (1); Retinopathy (1).